CRP (C-reactive protein)
Diseases named in the same sentence as CRP in open-access papers (continued):
Sharing a sentence is not in itself a finding about the gene and the disease.
COVID-19 (continued). "Among COVID-19 patients, the most common disorders of cytokines and chemokines are increased levels of IL-1β, IL-2, IL-6, interleukin-7 (IL-7), IL-10, TNF-α, CRP, chemokine ligand 2 (CCL2), as well as an increase or decrease in the concentration of IFN-γ." (PMID 36294388, 2022). "The current study has demonstrated the effectiveness of CRP, NLR, and WBC as predictors for in-hospital mortality among COVID-19 patients." (PMID 35628809, 2022). "The ROC curve was used to assess the predictive power of CRP, SAA, and WBC and lymphocyte and neutrophil counts in severe COVID-19 patients and their survival outcomes." (PMID 36465717, 2022). "The acute phase parameters C-reactive protein (CRP) and serum amyloid A (SAA) increased in parallel with COVID-19 severity reaching significance in all patients with moderate and severe COVID-19." (PMID 35265078, 2022). "According to the results of 21 patients in COVID-19 with ARDS who received siltuximab intravenously at doses between 700 and 1200 mg, CRP levels were significantly reduced in most patients." (PMID 35619180, 2022). "Several biochemical markers like C-reactive protein (CRP), interleukin-6 (IL-6), white cell count, lactate dehydrogenase (LDH), ferritin, albumin, and D-dimer predict COVID-19 outcome." (PMID 36084093, 2022). "This study shows that age, kidney disease, CREA, LD, CRP and LYM concentrations in COVID-19 patients from the southern region of Catalonia provide important information for their prognosis." (PMID 35210926, 2022). "There were significant differences between the non-COVID-19, mild-moderate-COVID-19, and severe-COVID-19 samples in terms of lymphocyte count, NLR, LDH, CRP, IL-6, and IL-8." (PMID 35687545, 2022). "The odds ratio (OR) values of IgG type, platelet, albumin, and lymphocyte were <1, respectively, and the OR values of age, C-reactive protein (CRP), COVID-19 IgM, and comorbidities were >1, respectively." (PMID 36081775, 2022). "Markedly, the COVID-19 Δ cohort showed surprisingly low levels of PCT and CRP, implying a mild infection with a weakened inflammatory response for hospitalized patients upon admission." (PMID 36062112, 2022). "While patients with mental health problems showed high levels of biomarkers, a meta-analysis, with 16 studies, evidenced higher counts of biomarkers (i.e. IL-6, CRP, PCT, among others) in severe cases of COVID-19." (PMID 36210450, 2022). "Significant markers which were commonly reported to be elevated in many studies of acute CVD and COVID-19 included ferritin, lactate dehydrogenase (LDH), D-dimer, C reactive protein (CRP), and troponin." (PMID 35203644, 2022). "Mothers with a severe course of COVID-19 had higher activated partial thromboplastin—APTT (p = 0.02), C-Reactive Protein—CRP (p = 0.00) and procalcitonin (p = 0.032) levels as compared to pregnant women with mild or moderate course of the disease." (PMID 36430023, 2022). "Furthermore, plasma CRP levels (marker of systemic inflammation) have been shown to correlate with deficits on the continuous performance test in recovered COVID-19 patients, suggesting that inflammation may play a role in cognitive complaints in remitted patients." (PMID 36033820, 2022). "A study showed C-reactive protein (CRP) was useful for monitoring the progression of infection and to detect severe cases of COVID-19 in the early phase." (PMID 35330449, 2022). "Evaluation of SGOT, CRP, ALC, LDH, WBC, O2sat, and ferritin levels in children with COVID-19 can be an indication for hospitalization and a predictor of disease severity, aiding clinicians in the management of patients." (PMID 35685588, 2022). "Targeted analysis of fecal metabolites showed significantly lower fecal concentrations of SCFAs in COVID-19 patients, which correlated with disease severity and increased plasma concentrations of CXCL-10 and CRP." (PMID 35956081, 2022). "Inflammatory indicators such as CRP, procalcitonin, ESR, interleukin-6 (IL-6), and ferritin are seen in COVID-19 patients." (PMID 36299504, 2022).
COVID-19 (continued). "The absolute number of leukocytes, the levels of CRP and the levels of creatine phosphokinase (CPK) were significantly higher in patients with severe COVID-19 than in moderate and mild COVID-19 groups." (PMID 36032130, 2022). "We analyzed the prognostic capacity of serum albumin (SA) and CRP for an outcome comprising mortality, length of stay, ICU admission, and non-invasive mechanical ventilation in hospitalized COVID-19 patients." (PMID 35740416, 2022). "There was a faster recovery of subjects from COVID-19 symptoms, along with a significant reduction in inflammatory markers like LDH ferritin, and CRP." (PMID 35783877, 2022). "Haematological tests were conducted on all MHCUs testing COVID-19 RT-PCR positive, the erythrocyte sedimentation rate (ESR) being elevated in nine (47.4%) and the C-reactive protein (CRP) also being abnormally increased in 8 of the 19 (42.1%)." (PMID 36569809, 2022). "We need to be more alert to the levels of CRP, ALP, serum lactate, albumin, neutrophils and regular monitoring of blood glucose, once diabetic cancer patients are infected with COVID-19." (PMID 36059615, 2022). "High serum cytokines, such as interleukin-6 (IL-6), inflammatory serum markers, such as ferritin, D-dimer, C-reactive protein (CRP), and peripheral lymphopenia are some characteristics of immunological signatures of COVID-19." (PMID 35458517, 2022). "In a meta-analysis of thirty-two studies, Malik and colleagues found significant associations between blood lymphopenia, thrombocytopenia, elevated CRP, procalcitonin, lactate dehydrogenase, D-dimer, ALT, and AST with adverse COVID-19 outcomes." (PMID 35680931, 2022). "Higher WBC counts, neutrophilcounts and percentages, D-dimer, CRP, procalcitonin, and APTT were observed inthe COVID-19 deaths group, while lower lymphocyte counts and percentages, andbasophil and monocyte percentages were observed in this group." (PMID 34550036, 2022). "They documented impressive responses with statistically significant improvements in laboratory results (methemoglobin, CRP, LDH) and clinical status (rapid reversal of hypoxia and recovery in severely ill COVID-19 subjects)." (PMID 36358582, 2022). "The use of vitamin E combined with vitamins A, C, B, and D, reduced ESR, CRP, IL-6, TNF-a, and hospitalization time in adults with COVID-19." (PMID 36295088, 2022). "Therefore, increased CRP and IL-6 might be related to the disease severity of COVID-19." (PMID 35037900, 2022). "In our study, we also found that NLR had the higher AUC value than LDH, CRP, SOFA and qSOFA with a cut-off level as 7.8 (83.33% sensitivity, 97.7% specificity) in terms of predicting the mortality in COVID-19 patients." (PMID 35468761, 2022). "As it was expected, there was highly significant correlation between plasma levels of CRP and AAT from COVID-19 patients." (PMID 36084115, 2022). "Multivariate regression analysis determined that age, C-reactive protein, D-dimer, hypertension, and HDL-C as independent predictors for the development of COVID-19 mortality." (PMID 35997994, 2022). "According to the previous studies, levels of the disease progression indicators CRP, PCT, IL-6, and D-dimer are found to be significantly higher in COVID-19 patients with hypocalcemia." (PMID 35678023, 2022). "In our study, inflammatory cytokines TNF-a, C-Reactive Protein (CRP), and Interleukin 6 (IL-6) significantly differed between patients with moderate and severe COVID-19, indicating their potential as parameters for severity." (PMID 36556051, 2022). "Inflammatory biomarkers such as C-reactive protein (CRP), D-dimer, and ferritin are often elevated in COVID-19 patients." (PMID 36560686, 2022). "In the present study, we observed differences in the routine laboratory data; bacterial sepsis patients showed higher procalcitonin (PCT) and C-reactive protein (CRP) values, while COVID-19 patients showed higher ferritin values." (PMID 35723762, 2022).
COVID-19 (continued). "IL-1α, IL-1β and ferritin were relatively increased in patients with COVID-19, particularly when compared with CAP-other and CAP-flu, whilst procalcitonin, IL-6 and CRP were highest in CAP-strep." (PMID 35660785, 2022). "Several inflammatory response markers including procalcitonin, serum ferritin, C-reactive protein (CRP), D-dimer, and interleukin-6 (IL-6), which have been found to correlate significantly with severity of disease and poorer outcomes of COVID-19 patients." (PMID 35160150, 2022). "The current paper adds important insights regarding the correlation between high values of CRP, fibrinogen, and ESR and the presence of acute coronary atherothrombosis in patients with COVID-19." (PMID 36362770, 2022). "Our study analyzed D-dimer, lactate, and inflammatory markers, including CRP, ferritin, and LDH that are of great interest in clinical settings and have been routinely ordered for COVID-19 patients." (PMID 35562677, 2022). "The following serum inflammatory biomarkers CRP, ferritin and LDH were assessed 6 months since COVID-19 diagnosis in symptomatic and asymptomatic patients." (PMID 35233035, 2022). "All of the biochemical parameters including CRP, LDH, and ferritin are usually elevated in COVID-19 patients and correlate with the severity of disease." (PMID 35203759, 2022). "The median levels of both CRP and SAA were greater in COVID-19 patients than in healthy controls after age adjustment (comparing age < 40 years in both COVID-19 patients and healthy controls)." (PMID 35958594, 2022). "A case series of 8 pregnant females showed a milder course of COVID-19 and recommended monitoring of TLC, lymphocyte count and CRP." (PMID 35371473, 2022). "This supports the use of CRP and PCT to detect newly emerging bacterial infections in pediatric COVID-19 patients." (PMID 35703526, 2022). "A meta-analysis showed that elevated CRP, elevated LDH, and lymphopenia were among the most prevalent laboratory findings in patients with COVID-19." (PMID 36560453, 2022). "In most studies, compared with healthy controls, COVID-19 patients had significantly higher levels of interleukin (IL)-2, IL-4, IL-6, IL-10, tumor necrosis factor (TNF)-α, and C-reactive protein (CRP) and lower lymphocyte counts." (PMID 35310853, 2022). "In a study involving 60 patients with severe stage of COVID-19, 100 mL of XBJ injection resulted in increased white blood cell (WBC) count and decrease in pro-inflammatory markers, such as C reactive protein (CRP) and erythrocyte sedimentation rate (ESR)." (PMID 35565876, 2022). "COVID-19 patients have average or decreased WBC count with reduced lymphocyte, and normal or increased CRP." (PMID 35419241, 2022). "In the present study, it was observed that CRP, LDH and vitamin D levels should be taken into account as biomarkers for COVID-19-positive pediatric patients." (PMID 36676040, 2022). "In line with previous reports, we have found that in COVID-19 patients, plasma LDH and CRP levels correlate with respiratory failure based on PaO2/FiO2 ratios." (PMID 36084115, 2022). "In a retrospective review of 168 patients hospitalized with COVID-19 in Wuhan, China, there were five biomarkers identified that were higher among men who died than among women who died (NLR, CRP, AST, LDH, and creatinine)." (PMID 35548417, 2022). "This discrepancy with higher CRP levels being associated with increased myosteatosis but lower SAT and IMAT has already been reported in the general population, leading us to hypothesise that the inflammatory state may favour a smaller decrease of the PMD in COVID-19 survivors as well." (PMID 36145141, 2022). "The levels of C-reactive protein (CRP), alanine transaminase, pro-calcitonin, lactate dehydrogenase, and ferritin were also significantly elevated in severe COVID-19 cases." (PMID 35154972, 2022).
COVID-19 (continued). "A retrospective study that included 440 COVID-19 patients showed that the GDF15 serum level was increased and positively correlated with C reactive protein (CRP), IL-6 and IL-8 in severely affected patients." (PMID 36140453, 2022). "Acute systemic inflammation markers, C-reactive protein (CRP) and ferritin were elevated in COVID-19 patients according to normal clinical parameters." (PMID 35173744, 2022). "Our data show elevated serum levels of CRP, LDH and ferritin in all COVID-19 patients, which are significantly higher in the ARDS group than in non-ARDS patients on hospital admission." (PMID 34439469, 2021). "The performed sensitivity analysis allowed us to figure out the core score components, which presumably reflect the fundamental properties of COVID-19 pathogenesis, namely APTT, CRP, D-dimer, glucose, hemoglobin, lymphocytes and urea." (PMID 34950678, 2021). "In contrast, CRP and SAA levels increased rapidly in all COVID-19 cases, and the levels of these two biomarkers were significantly higher in those with severe disease than in mild cases (all P < 0.05)." (PMID 33627079, 2021). "Lab values in most of COVID-19 patients show normal or low WBC count, elevated neutrophil ratio, serum C-reactive protein, procalcitonin and lactic dehydrogenase and decreased lymphocyte ratio and lymphocyte count." (PMID 33331164, 2021). "Silibinin-treated cancer/COVID-19+ patients required only minimal oxygen support (2–4 L/min) during the episode, exhibited a sharp decline of the STAT3-regulated C-reactive protein, and demonstrated complete resolution of the pulmonary lesions." (PMID 35056076, 2021). "Different to other frequently measured laboratory values such as hematological cell counts or creatinine, most patients had a distinct CRP maximum around ICU admission in our cohort, indicating a correlation with COVID-19 severity and progression." (PMID 34307391, 2021). "Neutropenia, leukopenia, lymphopenia, higher CRP, NLR, and PT correlated with COVID-19 patients’ mortality." (PMID 34904053, 2021). "Studies have already reported differences in the level of blood-based proteins such as lactate dehydrogenase (LDH), D-dimers, and inflammatory markers such as C-reactive protein (CRP), ferritin, and fibrinogen in COVID-19 patients." (PMID 33995121, 2021). "Labs were notable for the following elevated inflammatory markers: CRP 87 mg/dL, D-dimer 765 ng/mL, Ferritin 1245 ng/mL, and LDH 986 U/L, and his COVID-19 PCR was positive." (PMID 34512966, 2021). "Ca2+ in COVID-19 patients was significantly negatively correlated with PCT, calcitonin, D-dimer, PFDP, ESR, CRP and IL-6." (PMID 34222271, 2021). "Platelet count, procalcitonin, interleukin-6, C-reactive protein (CRP), erythrocyte sedimentation rate (ESR), serum ferritin, and other laboratory tests have been identified as markers for potential progression to COVID-19 critical illness." (PMID 33725003, 2021). "The COVID-19 ARDS Prediction Score (CAPS) was constructed using age (≥60 years old), C-reactive protein (≥5 mg/dL), and the infiltration on a chest X-ray (≥22%), with each predictor allocated 1 point." (PMID 33897912, 2021). "To further explore the contribution of TREM-2 in COVID-19, we analyzed the correlations of TREM-2 with disease indexes including C-reactive protein (CRP), lymphocyte count, and D-dimer, as well as age, which are considered as a risk factor in COVID-19." (PMID 34878838, 2021). "In one case report of compassionate use in severe COVID-19, administration of Wharton’s jelly-derived MSCs reduced plasma levels of IL-6, TNF-α, and C-reactive protein and improved lung function." (PMID 33584343, 2021). "High levels of CRP and erythrocyte sedimentation rate (ESR) have been previously reported in COVID-19 patients." (PMID 34568363, 2021). "The hyper-inflammatory state, where IL-6 and C-reactive protein (CRP) levels are raised, has been shown to predict severity of disease in some COVID-19 patients." (PMID 34834033, 2021).
COVID-19 (continued). "In line, along with elevated concentrations of OPN in COVID-19 patients, we found a strong correlation of OPN levels with different marker for systemic inflammation (CRP, lactate dehydrogenase D-dimer, ferritin, and procalcitonin)." (PMID 34501358, 2021). "During the acute COVID-19 phase, 16 patients required admission to ICU, mean C-reactive protein was 75.8 mg/L (SD 59.3), and mean P/F ratio was 279.86 (SD 78.5)." (PMID 34363587, 2021). "Patients with MIS-C showed higher plasma levels of C reactive protein (CRP), MPO, IL-6, and of the pro-inflammatory chemokines CXCL8 and CCL2 than COVID-19 children." (PMID 33841438, 2021). "In the biological parameters, we observed lower plasma concentrations of C-reactive protein (CRP), lactate and glucose in COVID-19 patients." (PMID 34031519, 2021). "Elevated serum C-reactive protein (CRP), a protein whose expression is driven by IL-6, is also a biomarker of severe clinical manifestations of COVID-19." (PMID 34185801, 2021). "When a machine learning-based model was applied, CRP, age, LDH, ferritin and IL-10 turned out to be predictors of COVID-19 related mortality." (PMID 34539644, 2021). "A retrospective single-center case series reported significant correlations between plasma troponin T (TnT) levels and the levels of high-sensitivity C-reactive protein (CRP) and N-terminal fragment of pro-BNP (NT-pro-BNP) in patients with COVID-19." (PMID 33404925, 2021). "Univariate logistic regression analysis on the factors that influenced mortality among the COVID-19-positive patients in the ICU, including male sex, cortisol level, CRP level and albumin level, showed significant results." (PMID 34190873, 2021). "We observed that the levels of inflammation indicators in severe COVID-19-infected patients, including ESR, CRP, and IL-6, were significantly increased." (PMID 34222271, 2021). "Some nonspecific inflammatory markers such as C-reactive protein (CRP), erythrocyte sedimentation rate (ESR), ferritin, fibrinogen, and D-dimers were found to be elevated in COVID-19." (PMID 34306612, 2021). "Most COVID-19 patients have very low PCT levels (moderate) at the time of admission, but elevated markers of inflammation such as white blood count (WBC) and C-reactive protein (CRP) indicate that they have inflammation in the lungs." (PMID 34336223, 2021). "Increases in many cytokines, especially CRP, sedimentation, ferritin, PRC, and IL-6, have been reported in COVID-19 patients." (PMID 34868686, 2021). "COVID-19 patients have shown interestingly higher levels of LDH, leukocytosis, CRP, and prolactin, which have been considered to be pivotal factors for ocular manifestations of COVID-19." (PMID 34595136, 2021). "At the time of diagnosis of COVID-19 patients, 45/117 (38.57%) had high levels of ALT, 104/117 (97.44%) had high levels of CRP and 48/117 (41.3%) had high levels of AST." (PMID 34834450, 2021). "FIB-4, HA, AST, LDH, CRP, ferritin, IL-6, and ESR at admission to the hospitals (acute COVID-19 group) were higher than in the post-COVID and the control groups." (PMID 34635073, 2021). "Myocardial injury (HR=4.55, 95% CI, 2.49-8.31, p<0.001), senior age, CRP levels, and novel coronavirus pneumonia (NCP) types on admission were independent predictors to mortality in COVID-19 patients." (PMID 33619471, 2021). "Cessation of dexamethasone in critically ill COVID-19 patients results in a rebound increase in PCT and CRP levels unrelated to the occurrence of secondary bacterial infections." (PMID 34353339, 2021). "Age, Temperature, Black, Troponin, Creatinine, WBC, C-Reactive protein, ALT, Glucose, BUN, INR, Platelets, and D-dimer were all related to mortality of COVID-19 individuals with hypotension and hypoxemia, according to univariate analysis." (PMID 34778315, 2021). "The patients who recovered from COVID-19 had significantly lower plasma levels of KYN, CRP, IL-6, ferritin, NTproBNP, cTnT, and creatinine." (PMID 34943063, 2021).